EEF1A2 (eukaryotic translation elongation factor 1 alpha 2)
Diseases named in the same sentence as EEF1A2 in open-access papers (continued):
Sharing a sentence is not in itself a finding about the gene and the disease.
tumor (continued). "Previous studies investigated that eEF1A2 (eukaryotic protein elongation factor 1 alpha 2) was identified as a protein translation factor that has a high expression in tumors of the ovary, breast, and lung." (PMID 36500178, 2022). "On the other hand, knockdown of EEF1A2 decreased the expression of IL-6 which is considered to play key roles in tumor immune evasion." (PMID 34446611, 2021). "As clinical data showed high expression levels of EEF1A2 in metastatic LUAD tumour tissues, we investigated the effect of EEF1A2 on metastatic ability of LUAD cells." (PMID 33473168, 2021). "For example, FRET-FLIM revealed the close distance between translation elongation factor eEF1A2 and an anti-tumor agent, plitidepsin, forming a drug-protein complexes in tumor cells." (PMID 34138374, 2021). "Subcutaneous and metastatic tumour mouse models revealed that EEF1A2 was a putative oncogene that promoted progression of LUAD in vivo." (PMID 33473168, 2021). "Most of the hub RBPs presented significant divergence between normal and tumor tissue except for EEF1A2." (PMID 33133154, 2020). "eEF1A2, an isoform of the eEF1A protein, is aberrantly upregulated in many tumor tissues and has been identified as a tumor‐associated protein." (PMID 31876369, 2020). "Altogether, these results show that the presence of eEF1A2–PKR complexes is necessary to inhibit the pro-apoptotic functions of PKR in tumour cells." (PMID 30420615, 2018). "It binds specifically to the alpha subunit of the eukaryotic Elongation Factor 1 (eEF1A2), resulting in tumour cell death via apoptosis." (PMID 30423952, 2018). "eEF1A2 is overexpressed in human tumours, favouring tumour cell proliferation and inhibiting apoptosis." (PMID 30423952, 2018). "Previous experiments have demonstrated that plitidepsin localises in tumour cells that are sufficiently close to the eEF1A2, indicating the formation of drug–protein complexes in the living cells." (PMID 30423952, 2018). "All in all, eEF1A2 emerges as an Achilles heel in tumour cells that can be targeted for anticancer therapy." (PMID 30420615, 2018). "Using plitidepsin to target eEF1A2, we demonstrate that the pro-oncogenic activities of eEF1A2 are important for the fitness and survival of tumour cells." (PMID 30420615, 2018). "On the contrary, the other EEF1A isoform namely EEF1A2, displayed significantly elevated mRNA levels in tumor tissues in 24 datasets and the opposite trend in 21 datasets." (PMID 29342219, 2018). "Overall TCGA analysis confirmed the same, indicating reduced EEF1A2 transcript levels in tumor tissues." (PMID 29342219, 2018). "Herein, we characterised a new signalling pathway through which eEF1A2 promotes tumour cell survival." (PMID 30420615, 2018). "More work is needed to ascertain the precise function(s) of eEF1A2 that is/are impaired by plitidepsin to induce tumor cell death so efficiently." (PMID 29348621, 2018). "Here we investigate the role of new “moonlighting functions” of eEF1A2 in the maintenance of tumour phenotype." (PMID 30420615, 2018). "The observation of eEF1A2–PKR complexes prompted us to investigate their biological role in tumour cells." (PMID 30420615, 2018). "qRT-PCR revealed EEF1A2 to be significantly overexpressed in PCa tissue, with an increase according to tumor stage in one cohort (p = 0.0443)." (PMID 28923030, 2017). "Eukaryotic translation elongation factor 1 alpha 2 (EEF1A2) was previously suggested as driver of tumor progression and potential biomarker." (PMID 28923030, 2017). "In summary, the results presented here demonstrate the critical role of the interaction between plitidepsin and eEF1A2 in its antiproliferative effect on tumor cells." (PMID 27713531, 2016). "FLIM-phasor FRET experiments demonstrated that plitidepsin localizes in tumor cells sufficiently close to eEF1A2 as to suggest the formation of drug-protein complexes in living cells." (PMID 27713531, 2016).
tumor (continued). "Three tumor cell lines selected for at least 100-fold more resistance to plitidepsin than their respective parental cells showed reduced levels of eEF1A2 protein." (PMID 27713531, 2016). "The importance of maintaining the control of eEF1A levels is highlighted by the oncogenic properties of eEF1A2, whose inappropriate expression has been shown to induce tumour growth." (PMID 27807005, 2016). "For example, the relationship between oxidative stress, one of the main events involved in tumor cell death induced by plitidepsin, and its targeting of eEF1A2 is not fully understood yet." (PMID 27713531, 2016). "Three out of four tumour and all peritumoural hyperplasia samples resulted positive for EEF1A2 gene expression." (PMID 22095224, 2012). "The data presented here indicate that EEF1A2 is aberrantly expressed at high levels in some plasma cell neoplasms of mice and humans." (PMID 20505761, 2010). "This is the first example of EEF1A2 being expressed in a mouse tumor, although high-level expression has been documented in a variety of human tumors belonging to different cell lineages." (PMID 20505761, 2010). "eEF1A2 protein is expressed at detectable levels in most clear cell tumours (four out of five tumours analysed; 80%), but only one out of 23 serous papillary tumours and two out of 11 endometrioid tumours." (PMID 17437010, 2007). "Initially, we carried out real-time RT–PCR to assess the level of expression of eEF1A2 mRNA in the tumour panel." (PMID 17437010, 2007). "We have developed specific anti-eEF1A2 antibodies and used them in immunohistochemical analyses of tumour samples." (PMID 16156888, 2005). "Of the tumour samples, 5 showed strong expression of eEF1A2 (11%) and 22 showed moderate expression (48%)." (PMID 16156888, 2005). "Likewise, western blot analysis and IHC on tissue microarrays also showed EEF1A2 protein to be moderately or strongly overexpressed selectively in tumor tissues compared with normal liver." (PMID 38172654, 2024). "EEF1A2 was previously suggested as driver of tumor progression and potential biomarker." (PMID 37968615, 2023). "Additionally, western blot results verified that EEF1A2 protein expression decreased in tumour tissues of the sh-EEF1A2 group." (PMID 33473168, 2021). "Furthermore, the ectopic expression of DDX5 and eEF1A2 also weakened the inhibitory effects of DRD2 on tumor proliferation as assessed by CCK8 and Transwell® assay." (PMID 33859743, 2021). "As expected, EEF1A2 knockdown delayed tumour growth in mice xenografts." (PMID 33473168, 2021). "Notably, EEF1A2 expression was further enhanced in advanced-stage and distant-metastatic tumour tissues." (PMID 33473168, 2021). "Thus, our results suggested that eEF1A2 is indispensable for SNX16‐mediated tumor‐promoting functions in CRC cells." (PMID 31876369, 2020). "Moreover, the isoform eEF1A2 is overexpressed in many human tumors and transformed cell lines, favoring tumor cell proliferation while inhibiting apoptosis." (PMID 29348621, 2018). "Plitidepsin, through its binding to eEF1A2, would release the apoptotic brake imposed by this elongation factor, exposing the frailty of the tumour cells, especially when compared with healthy tissues expressing eEF1A2, and leading them to a PKR-dependent apoptotic cell death." (PMID 30420615, 2018). "Interestingly, for EEF1A2, significantly reduced levels in tumor were observed in four unique analyses." (PMID 29342219, 2018). "EEF1A2 was significantly overexpressed in these tumor samples." (PMID 28923030, 2017). "Reports on EEF1A2 expression in other tumor entities show differing results." (PMID 28923030, 2017). "Although preliminary, all of these results suggest that, by interacting with eEF1A2, plitidepsin could be affecting distinct functions of this protein in tumor cells." (PMID 27713531, 2016). "Our data obtained with several tumor cell lines support the hypothesis that eEF1A2 is the main target responsible for plitidepsin’s antiproliferative effects." (PMID 27713531, 2016).
tumor (continued). "This may suggest a role for eEF1A2 in sustaining both protein translation (cytoplasmic fraction) and cytoskeletal reorganisation (cytoskeletal–nuclear fraction) in the tumour cells studied." (PMID 22095224, 2012). "There are numerous reports of the cytoskeletal modifying properties of eEF1A1; again, these might differ from eEF1A1 to eEF1A2 and possibly relate to tumour invasion and propensity to metastasize." (PMID 17437010, 2007). "The similar pattern of copy number changes between non-expressing and expressing tumours suggests that gene amplification is not the primary mechanism underlying the overexpression of eEF1A2." (PMID 17437010, 2007). "Consequently nucleotide exchange in this latter isoform must be impaired as is its functionality in aminoacyl-tRNA delivery to the ribosome, a hypothesis that casts doubts on the actual role of eEF1A2 in translation when abnormally over-express in tumor cells." (PMID 27713531, 2016). "Therefore, we can infer that the antiproliferative effects of the drug in tumor cells could not only be ascribed to its selectivity towards eEF1A2, but probably to the selective role of the latter with respect to eEF1A1 in promoting oncogenic transformations." (PMID 27713531, 2016). "We can also speculate that the reported direct interaction of eEF1A2 with peroxiredoxin-18 could also be perturbed by plitidepsin and this might be responsible for the potent oxidative stress that is observed after exposure of tumor cells to the drug." (PMID 27713531, 2016). "Also in the 22Rv1 cells, characterised by a growth rate comparable to LNCaP, the EEF1A1 mRNA levels did not significantly differ from those of PZHPV-7, whereas a significant (P=0.02) increase of EEF1A2 mRNA levels were found as in the other tumour cell lines tested." (PMID 22095224, 2012). "Finally, we sequenced the coding and untranslated regions of the EEF1A2 gene in those tumours, which were overexpressing eEF1A2, but which had low copy number (and were thus amenable to analysis by sequencing without the potential complication of sequence differences between gene copies)." (PMID 17437010, 2007). "They focused on eEF1A2, a protein that regulates tumor progression via PTM, which led to identifying KAT8 as the “writer” responsible for eEF1A2-Kla." (PMID 40484921, 2025). "EEF1AKMT4 trimethylates eEF1A2 at K36 site in GBC and is essential for the tumor-promoting effect of eEF1A2." (PMID 41705259, 2025). "Overall, our results revealed that EEF1A2 interacted with HSP90AB1 to activate SMAD3 signalling and promote tumour metastasis." (PMID 33473168, 2021). "When DRD2 located in cellular membrane, it exerted anti-tumor effects through downregulating DDX5 and eEF1A2." (PMID 33859743, 2021). "TCGA analysis further confirmed that mRNA levels of EEF1A1, EEF1A2, EEF1B2, EEF1G and EEF2 were significantly downregulated in tumor tissues than normal." (PMID 29342219, 2018). "LOC80078 and LOC101930114 were the most significantly up- and down-regulated DELs; EEF1A2 and ANKRD1 were the most significantly up- and down-regulated DEMs in TNM I stage LUAD tissues compared to paired non-tumor tissues." (PMID 28881680, 2017). "In vitro testing via siRNA-interference of EEF1A2 revealed a reduction of PC3 cell migration, indicating a potential tumor promoting function." (PMID 28923030, 2017). "The overexpression of eEF1A2 in Swiss NIH3T3 cells results in an enhanced growth rate, anchorage-independent growth and an induced tumour formation when xenografted in nude mice." (PMID 27807005, 2016). "In the same paper, forced expression of eEF1A2 in cells was demonstrated to confer tumourigenic properties on NIH3T3 cells, and to give rise to tumours in xenografted nude mice." (PMID 16156888, 2005).
tumor (continued). "Targeting EEF1A2 and plitidepsin to release protein kinase R may trigger the extrinsic pathway of MAPK and nuclear factor-κB–dependent activation, leading to tumor cell death." (PMID 34220510, 2021). "However TCGA analysis revealed that in addition to EEF1E1, mRNA levels of EEF1A2, EEF1G, and EEF1D are also significantly upregulated in tumor tissues." (PMID 29342219, 2018). "It revealed that while mRNA levels of other translation factors were not significantly different between tumor and normal samples, EEF1A2 mRNA levels were comparatively higher in tumor samples." (PMID 29342219, 2018). "However, significant overexpression of EEF1A2, EEF1G, EEF1D, EEF1E1 and EEF2 was seen in tumor tissues." (PMID 29342219, 2018). "Elevated levels of eEF1A2 have been found in many tumours, and expression of eEF1A2 in non-native tissues is known to induce tumorigenesis." (PMID 27807005, 2016). "We used bisulphite sequencing to compare the methylation profile of 548 bp of the CpG island at the 5′ end of the EEF1A2 gene in DNA samples from normal ovary, from tumours that do not express eEF1A2 and from overexpressing tumours." (PMID 17437010, 2007). "Amplification was seen just as frequently in tumours that do not express eEF1A2; it would be of interest to examine the expression levels of other genes within this amplicon." (PMID 17437010, 2007). "We did not have access to cell lines from the tumours we had studied at the RNA and Western level, but did have DNA, so we used a real-time PCR method to estimate the copy number of the EEF1A2 locus." (PMID 17437010, 2007). "The difference in eEF1A2 expression levels between the estrogen receptor negative tumours and estrogen receptor positive tumours is 7.2 units (P = 0.0087, t-test, 95% confidence interval 2.0 to 12.4 units)." (PMID 16156888, 2005). "Targeting eEF1A2 with plitidepsin releases PKR from the complex, facilitating its activation and triggering a mitogen-activated protein kinase signalling cascade together with a nuclear factor-κB-dependent activation of the extrinsic apoptotic pathway, which lead to tumour cell death." (PMID 30420615, 2018). "It is clear therefore that overexpression does not depend on genetic or epigenetic changes at the EEF1A2 locus; we suggest that the overexpression may be mediated by the inappropriate expression of a trans-acting factor in certain tumours." (PMID 17437010, 2007). "None of the five tumours with a mucinous component had detectable eEF1A2 expression." (PMID 17437010, 2007). "This may suggest that the mechanism of overexpression of eEF1A2 in the tumours does not necessarily lead to the production of a stable protein." (PMID 17437010, 2007). "The copy number at the EEF1A2 locus does not correlate with expression level of the gene, no functional mutations were found, and the gene is unmethylated in both normal and tumour DNA, showing that overexpression is not dependent on genetic or epigenetic modifications at the EEF1A2 locus." (PMID 17437010, 2007). "EEF1A1 may be predictor of good prognosis, not due to the direct involvement of EEF1A1 imparting anti-tumor activities, rather the correlation of its higher expression levels with lower levels of the proto-oncogenic isoform EEF1A2, thereby serving as a biomarker indirectly." (PMID 29342219, 2018). "The eEF1A2 gene is unmethylated both in normal and tumor cells, suggesting that up-regulation of eEF1A2 gene expression is not dependent on epigenetic modifications (at least for the methylation status), but instead that the inappropriate expression of trans-acting factor(s) could be involved." (PMID 25905039, 2015). "It is clear that there is no obvious correlation between copy number and gene expression; indeed, a non-expressing tumour, number HOV170, shows the greatest EEF1A2 copy number." (PMID 17437010, 2007).
neurodevelopmental disorder (9 papers, 2017 to 2026). A behavioral and cognitive disorder with onset during the developmental period that involves impaired or aberrant development of intellectual, motor, or social functions. "Collectively, current evidence supports a causal role for eEF1A2 in neurodevelopmental disorders but only a contributory role in neurodegenerative conditions." (PMID 42077067, 2026). "Developmental and epileptic encephalopathies (DEEs) are rare neurodevelopmental disorders (NDDs) resulting from mutations in any one of over 200 genes, including EEF1A2." (PMID 38179821, 2024). "De novo heterozygous missense mutations in the gene encoding translation elongation factor eEF1A2 have recently been found to give rise to neurodevelopmental disorders." (PMID 28378778, 2017). "De novo missense mutations in the human gene EEF1A2, encoding a tissue-specific translation elongation factor, cause severe neurodevelopmental disorders; there is a real need for a model system to study these disorders and we wanted to explore the possibility of a zebrafish model." (PMID 31950975, 2020). "The E122K/+ mouse model will be valuable for preclinical proof-of-concept studies investigating different therapeutic approaches in EEF1A2-related neurodevelopmental disorder." (PMID 38179821, 2024). "Remarkably, Cys411 in both eEF1A1 and eEF1A2 is known to be glutathionylated in response to glucose starvation and this residue in the eEF1A2 dimer is found spatially close to Pro333, an amino acid that is replaced by Leu in some children suffering from neurodevelopmental disorders." (PMID 34203525, 2021).
adenocarcinoma (8 papers, 2013 to 2025). A common cancer characterized by the presence of malignant glandular cells. "Higher EEF1A1 levels in adenocarcinoma correlated with better OS and FP, while higher EEF1A2 levels predicted worse OS and FP." (PMID 29342219, 2018).
neurological disorders (4 papers, 2016 to 2025). "The tissue-specific protein eEF1A2 has been linked to the development of neurological disorders." (PMID 37051183, 2023). "Zebrafish (Danio rerio) could provide a valuable model system for neurological disorders resulting from mutations in eEF1A2, but relatively little is known about eEF1A in zebrafish." (PMID 31950975, 2020). "Furthermore, accumulating data show that eEF1A2 has a significant association with nervous system diseases." (PMID 26918757, 2016). "An increasing number of studies have shown that eEF1A2, in addition to its anti-apoptotic properties in many cancers, has an important role in nervous system diseases." (PMID 26918757, 2016). "There are several lines of evidence implicating eEF1A2 in neurological disorders." (PMID 31950975, 2020). "Our present findings suggest that eEF1A2 may be a potential new therapeutic target for nervous system diseases." (PMID 26918757, 2016).
neurodegenerative disease (3 papers, 2013 to 2023). A disorder of the central nervous system characterized by gradual and progressive loss of neural tissue and neurologic function. "Our findings define a mode of proteasomal activation through the change in proteasome composition driven by EEF1A2 and its spatial regulation, and are useful to formulate therapies to prevent neurodegenerative diseases." (PMID 37433777, 2023).
hematopoietic neoplasms (1 paper, 2010). "To gain further insight into the consequences of Eef1a2 knockdown in PCT, we performed gene expression profiling using a 384 well qPCR array enriched for genes known to be involved in hematopoietic neoplasms." (PMID 20505761, 2010).
intestinal disorder (1 paper, 2022). A non-neoplastic or neoplastic disorder that affects the small or large intestine. "We describe the case of a 17-year-old girl affected by ASD, reduced growth, neurological development delay, mutations in the PGM1 and EEF1A2 genes (in the absence of clinically manifested disease) and, intestinal disorders such as abdominal pain and diarrhea associated with weight loss." (PMID 35955962, 2022).